AMH (anti-Mullerian hormone)
Diseases named in the same sentence as AMH in open-access papers (continued):
Sharing a sentence is not in itself a finding about the gene and the disease.
hypopituitarism (1 paper, 2026). A condition of diminution or cessation of secretion of one or more hormones from the anterior pituitary gland. "However, the AMH levels were strongly increased corresponding to the underlying PCOS phenotype A. Most patients with congenital hypopituitarism show decreased or low-normal AMH levels, while patients with late-onset pituitary dysfunction are usually with normal hormonal concentrations." (PMID 41515619, 2026).
intrahepatic cholestasis (1 paper, 2025). A cholestasis characterized by impairment of the bile flow caused by obstruction located in the liver. "Moreover, in naturally conceived women, low maternal AMH levels in the first trimester are predictive of PIH, and abnormal AMH levels are associated with preterm birth and intrahepatic cholestasis of pregnancy." (PMID 40885958, 2025).
intrauterine growth restriction (1 paper, 2019). "In animal studies, exposure of chronic inflammation in pregnant rats using intraperitoneal lipopolysaccharide injections resulted in intrauterine growth restriction and was associated with significantly lower levels of serum AMH in offspring." (PMID 31511566, 2019).
ischemic stroke (1 paper, 2022). A stroke disorder caused by obstruction of blood flow to the brain, due to thrombotic (local blood clot formation) or embolic (due to a blood clot or other material traveling from another site) event. "According to the results from stage one and stage two, we confirmed that higher methylation levels of 17 targets in AMH, C17orf82, HDAC9, IGFBP3, LRRC10B, PDE3A, PRDM6, SYT7 and TBX2 genes were associated with a lower risk of ischemic stroke." (PMID 35345488, 2022). "Methylation of AMH, C17orf82, HDAC9, IGFBP3, LRRC10B, PDE3A, PRDM6, SYT7 and TBX2 was significantly associated with ischemic stroke." (PMID 35345488, 2022). "Higher methylation levels of 18 targets in AMH, C17orf82, HDAC9, IGFBP3, LRRC10B, PDE3A, PRDM6, SYT7 and TBX2 genes were associated with a lower risk of ischemic stroke." (PMID 35345488, 2022). "The results showed that the mean methylation levels of AMH, C17orf82, HDAC9, IGFBP3, LRRC10B, PDE3A, PRDM6, SYT7 and TBX2 were significantly (Wilcoxon's two sample test) lower in ischemic stroke cases than in controls." (PMID 35345488, 2022).
Kallmann syndrome (1 paper, 2022). Kallmann syndrome (KS) is a developmental genetic disorder characterized by the association of congenital hypogonadotropic hypogonadism (CHH) due to gonadotropin-releasing hormone (GnRH) deficiency, and anosmia or hyposmia (with hypoplasia or aplasia of the olfactory bulbs). "In our cohort, four patients (cases 24-25) had a classical clinical picture of Kallmann’s syndrome, but a boy (case 23) with the ANOS1 variant p.Gln586 had increased serum testosterone levels but did not have enlargement of testis after the long HCG test with normal inhibin B and AMH levels." (PMID 35432193, 2022).
Leydig cell tumor (1 paper, 2017). A sex cord-stromal tumor occurring in the testis and rarely in the ovary. "Thus, the TSC autochthonous tumors that grow spontaneously in SJL.AMH-SV40Tag transgenic mice have many of the characteristics of Leydig cell tumors but also express AMH, a marker traditionally associated with tumors of Sertoli cell origin." (PMID 28428886, 2017). "In contrast, testis tissue taken from 75 week-old male SJL.AMH-SV40Tag mice show transformed Leydig cell tumors in the interstitial space between seminiferous tubules." (PMID 28428886, 2017). "Thus, the well-documented, established characteristics of Leydig cell tumors correlated well with the observed features of the autochthonous TSC tumors that develop in SJL.AMH-SV40Tag transgenic mice." (PMID 28428886, 2017).
lipid metabolism disorders (1 paper, 2024). "Hormones and glucose and lipid metabolism disorders are important factors, considering the influence factors of AMH." (PMID 38600539, 2024).
lung adenocarcinoma (1 paper, 2024). A carcinoma that arises from the lung and is characterized by the presence of malignant glandular epithelial cells. "We hypothesized that the therapeutic effect of AMH may be applicable to lung adenocarcinomas with high AMHR2 expression." (PMID 39230026, 2024).
menopause (1 paper, 2013). Cessation of menstruation, occurring in (e.g.) the human female usually around the age of 50. "Under the hypothesis that menopause can be predicted by AMH dropping below a critical threshold, a model predicting menopausal age was constructed from the AMH regression model and applied to the data on menopause." (PMID 23505417, 2013).
Menorrhagia (1 paper, 2022). Prolonged and excessive menses at regular intervals in excess of 80 mL or lasting longer than 7 days. "In this study, LNG-IUD use in reproductive-age women diagnosed with menorrhagia decreased E2 levels, did not change LH levels, and increased FSH, AFC, and AMH levels." (PMID 36569727, 2022). "In the current study, we found a decrease in E2, an increase in FSH and AMH, and no change in LH at six months after versus prior to LNG-IUD insertion in the setting of menorrhagia." (PMID 36569727, 2022).
muscular atrophy (1 paper, 2023). The loss of muscle tissue due to inactivity or disease. "Here, we evaluated the effects of enzyme-assisted hydrolysates of Mytilus edulis prepared using Protamex (PMH), Alcalase (AMH), or Flavourzyme (FMH) in protecting against muscle atrophy in a dexamethasone (Dex)-induced muscular atrophy model in vitro and in vitro." (PMID 38132945, 2023).
myoma (1 paper, 2021). "In our study, we simply investigated the association of serum AMH changes and the FIGO type of the largest myoma in the LM group." (PMID 34300243, 2021).
neuroblastoma (1 paper, 2021). Neuroblastoma (NB) is the most common solid, extracranial childhood tumor. "SUCRA analysis showed that female neuroblastoma survivors were more at risk for reduced serum AMH levels and increased risk of POI." (PMID 34944951, 2021). "Women treated for a neuroblastoma during infancy were more likely to be ranked first for impaired AMH levels (SUCRA = 65.4%), followed by mixed CCS (SUCRA = 29.6%)." (PMID 34944951, 2021). "Similar to neuroblastoma survivors, there were reduced levels of AMH, inhibin B, and AFC when a TBI regimen was used." (PMID 34944951, 2021). "However, according to the SUCRA analysis, neuroblastoma survivors during infancy seem more prone to have impaired AMH levels, followed by unselected female CCS." (PMID 34944951, 2021). "Seven studies compared the AMH levels in mixed (including hematologic, lymphoid, and solid tumors) CCS, neuroblastoma survivors, and controls to indirectly test the ovarian reserve." (PMID 34944951, 2021).
non-alcoholic fatty liver disease (1 paper, 2025). "Factor 2 (Liver, Lipid, and Ovarian Function) comprises SGOT (0.97), VLDL (0.65), and AMH (0.47), aligning with Group C’s elevated SGOT and VLDL, suggesting potential non-alcoholic fatty liver disease (NAFLD)." (PMID 41220482, 2025).
non-small cell lung carcinoma (1 paper, 2020). A group of at least three distinct histological types of lung cancer, including non-small cell squamous cell carcinoma, adenocarcinoma, and large cell carcinoma. "AMH signaling regulates BMP, Akt, NF-κB (nuclear factor-κB), and SMAD signaling in non-small-cell lung cancer cells, and influences cell survival." (PMID 32060352, 2020).
oligohydramnios (1 paper, 2023). A lower than normal quantity of amniotic fluid in the amniotic sac as compared to normal values. "Moreover, in women with multiple deliveries, we demonstrated that high levels of AMH increased the risk of ICP, GDM and PIH, while low AMH levels are associated with an increased risk of ICP and oligohydramnios." (PMID 36896183, 2023).
orchitis (1 paper, 2024). Inflammation of one or both testes due to viral or bacterial infections. "Furthermore, AMH and Ki67 expression in SCs is a distinctive marker of severe alterations of STs in human orchitis." (PMID 38666890, 2024).
ovarian granulosa cell tumor (1 paper, 2025). A granulosa-stromal cell tumor that arises from the ovary. "The serum AMH level is directly proportional to the size of ovarian granulosa cell tumors and has a direct correlation with imaging results." (PMID 40597965, 2025).
pancreatic cancer (1 paper, 2022). "Genes that were upregulated in low-MUC1 PDA samples (MAPK12, RASD1, and AMH) were found to be favorable for OS in pancreatic cancer (Human protein atlas)." (PMID 35237602, 2022).
Primary hypothyroidism (1 paper, 2021). A type of hypothyroidism that results from a defect in the thyroid gland. "Thus, it would be important to assess the ovarian reserve (AMH and AFC) in individuals with primary hypothyroidism before the initiation of the treatment." (PMID 33752726, 2021).
primary Sjögren’s syndrome (1 paper, 2025). "In this study, we explored the potential effect of primary Sjögren’s syndrome on ovarian reserve, revealing that patients with pSS had significantly lower levels of AMH compared to age-matched controls." (PMID 39576415, 2025).
Psychological distress (1 paper, 2025). "Psychological distress could have led to drastic hormonal changes in this group within our sample, and a subsequent decline in AMH levels." (PMID 41196903, 2025).
rheumatic diseases (1 paper, 2024). "Different authors have shown that women with rheumatic diseases often exhibit reduced AMH levels compared to healthy controls, but few studies have been executed to assess fertility in patients with SSc." (PMID 39320461, 2024).
sex chromosomal DSD (1 paper, 2020). "In sex chromosomal DSD, where the gonads are more or less dysgenetic, AMH levels are indicative of the amount of functioning testicular tissue." (PMID 33013698, 2020).
sickle cell disease (1 paper, 2021). Sickle cell anemias are chronic hemolytic diseases that may induce three types of acute accidents: severe anemia, severe bacterial infections, and ischemic vasoocclusive accidents (VOA) caused by sickle-shaped red blood cells obstructing small blood vessels and capillaries. "Larger longitudinal studies of serum AMH and other markers of ovarian reserve are necessary in women with sickle cell disease, to corroborate our findings." (PMID 34895288, 2021).
state anxiety (1 paper, 2024). "↓ mFG score, LH, LH/FSH, AMH, Total testosterone, FI, FBG, HOMA-IR, TC, TG, LDL, VLDL, TC/HDL, trait anxiety (STAI)↑ HDL, menstrual cycle frequency and quality of life (PCOSQ)↔ weight, BMI, WC, WHR, FSH, Prolactin, and state anxiety.Adverse events not reported." (PMID 38818503, 2024).
synovitis (1 paper, 2021). Inflammation of a synovial membrane. "Also the AMH were correlated with the higher bone metabolic markers, lower bone mineral density, higher synovitis markers." (PMID 33654174, 2021).
systemic sclerosis (1 paper, 2024). A chronic disorder, possibly autoimmune, marked by excessive production of collagen which results in hardening and thickening of body tissues. "AMH levels were significantly reduced in patients with systemic sclerosis (955 ng/l versus 1.940 ng/L, p < 0.01)." (PMID 39320461, 2024). "For women diagnosed with systemic sclerosis, especially at a younger age, regular assessment of AMH levels should be considered to improve guidance with regard to optimal pregnancy timepoint, fertility preservation and treatment options." (PMID 39320461, 2024).
testicular cancer (1 paper, 2024). A primary or metastatic malignant neoplasm that affects the testis. "Additionally, AMH levels may be useful for assessing testicular damage across the lifespan, pre- and post-chemotherapy interventions, as a potential tumor marker in testicular cancer, and for determining health effects in male relatives of women with polycystic ovarian syndrome (PCOS)." (PMID 39032500, 2024).
thalassemia (1 paper, 2026). An inherited blood disorder characterized by a decreased synthesis of one of the polypeptide chains that form hemoglobin. "Additionally, AMH levels were significantly higher among women with thalassemia [2.58 ng/mL (IQR: 1.59–4.28) vs. 1.99 ng/mL (IQR: 1.12–3.32), p < 0.001]." (PMID 41607608, 2026). "In conclusion, while women with thalassemia exhibited higher unadjusted euploid embryo counts, these differences were not significant after adjustment for age, BMI, and AMH." (PMID 41607608, 2026).
thyroid cancer (1 paper, 2021). "Concerning the effects of 131-I used for differentiated thyroid cancer, AMH levels in long-term follow-up women seem unaffected by the therapy." (PMID 34944951, 2021).
vitiligo (1 paper, 2024). Generalized well circumscribed patches of leukoderma that are generally distributed over symmetric body locations and is due to autoimmune destruction of melanocytes. "The study found a negative correlation between the duration of vitiligo and AMH, prolactin, and ovarian volume, indicating that longer exposure to the disease may be associated with reduced ovarian reserve." (PMID 39717103, 2024).
ZIKV infection (1 paper, 2022). "In this study, we found that the significantly decreased mRNA levels of GDF-9, EPAB, and BMP-15 and unaltered AMH after ZIKV infection can impede follicular development to the antral stage." (PMID 34730391, 2022).
Zinc deficiency (1 paper, 2024). A deficiency of the essential metal Zinc; an essential cofactor for many enzymes. "The reduced concentration of anti-Müllerian hormone (AMH) in the serum further supported that the ovarian reserve was diminished in zinc deficiency mice." (PMID 38807213, 2024).
cancer (35 papers, 2010 to 2025). A tumor composed of atypical neoplastic, often pleomorphic cells that invade other tissues. "AMH is selectively expressed in epithelial cells versus mesenchymal cells and a loss of AMH is known to induce EMT in various cancers." (PMID 29986714, 2018). "As time interval since cancer treatment increased, AMH values declined in our cohort; the potential of recovery being low, especially in patients aged >40 years." (PMID 38806697, 2024). "AMH levels are, therefore, important information for oncologists whose patients are facing pre-menopause due to cancer treatment." (PMID 37152067, 2023). "AMH information can also be used to assess ovarian depletion after chemotherapy or endocrine therapy in cancer survivors." (PMID 37152067, 2023). "Further investigations are needed to elucidate the evolutionary processes that lead to these aSNPs in the AMH gene pool and the role of aSNPs in PDAC risk, and more broadly, to explore the Neandertal legacy in the susceptibility to other cancer types." (PMID 37574541, 2023). "In cancer patients, ovarian stimulation should be tailored according to age, basal AMH (anti-Müllerian hormone), ultrasound AFC (antral follicle count), and possible hormone-sensitive tumor malignancy type." (PMID 35326578, 2022). "Researchers have developed a method to protect oocyte reserve by administrating recombinant AMH during cancer treatment." (PMID 34946285, 2021). "Previous studies have researched the fluctuations AMH levels before, during, and after treatment for cancer in young women." (PMID 34944951, 2021). "Anti-mullerian hormone (AMH) shows promise to be used as a hormonal marker of reduced ovarian reserve in women who have been treated for cancer." (PMID 33429908, 2021). "In the field of oncology, AMH is useful for assessing ovarian function and advising patients before and after cancer treatment; therefore, it is promising for improving information and decision-making." (PMID 32656076, 2020). "AMH levels in the cancer group were lower than that of the non-cancer group (1.11 [0.08–4.65] ng/ml vs. 3.99 [1.19–8.7]; p-value <0.001)." (PMID 32185016, 2019). "It was found that the probability of AMH protein expression was significant depending on the average breastfeeding time (p = 0.004), the type of cancer (p = 0.006) and menstrual years (p = 0.045)." (PMID 30884769, 2019). "In vivo and in vitro studies have shown that AMH inhibits cell cycle and induces apoptosis in cancers with AMH receptors." (PMID 30884769, 2019). "The mean AMH level for cancer patients was 1.11 ng/ml (0.08–4.65 ng/ml), and for non-cancer patients 3.99 ng/ml (1.19–8.7 ng/ml)." (PMID 32185016, 2019). "This study showed that the AMH levels in reproductive age patients before receiving therapy were lower in contrast to that in the non-cancer patients (1.11 ng/ml vs. 3.99 ng/ml; p- value <0.001)." (PMID 32185016, 2019). "Our study found that the decreasing level of AMH in cancer group before therapy was related to older of biological age." (PMID 32185016, 2019). "In conjunction with AMH expression, this coincides with a good prognosis in the hormone-dependent type of cancer." (PMID 30884769, 2019). "There was statistically significant differentiation of AMH protein expression between cancer types (Kruskal–Wallis ANOVA, H (7, N = 232) = 20.636, p = 0.004)." (PMID 30884769, 2019). "Vanet al. also conducted a broader study in 2014 comparing the AMH levels in young cancer patients (<18 years) before treatment with non-cancer patients (age-matched)." (PMID 32185016, 2019). "The AMH levels in the blood of the cancer group were found to be significantly lower in contrast to those in the non-cancer group (1.11 [0.08-4.65] ng/ml vs. 3.99 [1.19- 8.7]; p- value <0.001)." (PMID 32185016, 2019). "There was no statistically significant differentiation between the mean expression of the AMH protein in the stages of cancer according to FIGO (Kruskal–Wallis ANOVA, H (9, N = 231) = 12.819, p = 0.171)." (PMID 30884769, 2019).